EMP3 (epithelial membrane protein 3 (MAM blood group))
Diseases named in the same sentence as EMP3 in open-access papers (continued):
Sharing a sentence is not in itself a finding about the gene and the disease.
glioma (continued). "Previous results suggested that EMP3 was a critical biomarker in glioma prognosis 28-32." (PMID 32328202, 2020). "Another bioinformatics analysis though significant analysis of microarray (SAM) identified that EMP3 could be used to estimate glioma patient prognosis." (PMID 33123464, 2020). "In glioma, the function of EMP3 as a tumor suppressor gene still remains to be controversial." (PMID 27527869, 2017). "Further, the differential function of EMP3 in glioma (as oncogene or tumor suppressor gene) might depend on the pathological grades (low grade glioma or GBM), genetic background (1p/19q LOH or 1p/19q retained) or glioma subtypes." (PMID 27527869, 2017). "The contrary function that EMP3 exerts in glioma might reflect the differential requirement for EMP3/TGF-β signaling to regulate tumor progression in low grade glioma or primary GBM." (PMID 27527869, 2017). "Accumulated evidence suggested that EMP3 might be a tumor suppressor gene in glioma, neuroblastoma, esophageal squamous cell carcinoma (ESCC) cell lines, and non-small cell lung cancer (NSCLC)." (PMID 26472188, 2015). "The EMP3 methylation status was successfully determined by MS-PCR in 193 of 229 gliomas (84.3%)." (PMID 24083241, 2013). "The EMP3 promoter hypermethylation has been found in 39.5% of gliomas." (PMID 24083241, 2013). "In the present study the EMP3 promoter hypermethylation has been found in 39.5% of gliomas." (PMID 24083241, 2013). "In the whole series of 185 glial tumors, the EMP3 hypermethylation was associated with loss of the 19q13.3 locus, as defined by loss of the two consecutive MLPA probes ZNF342 and PPP1R15A, tightly flanking the EMP3 gene (P = 0.0001)." (PMID 24083241, 2013). "By cDNA microarray expression profiling, the EMP3 promoter hypermethylation has been found to be differentially expressed in low-grade gliomas with and without 19q13.3 loss." (PMID 24083241, 2013). "Interestingly, EMP3 expression is found to be altered in glioma tissue, but the gene expression status and biological function of EMP3 in glioblastoma remains unknown and unclear." (PMID 38229014, 2024). "Based on our observations and tests, we determined that EMP3 may still be an oncogene in glioma." (PMID 37091145, 2023). "According to previous studies, CHI3L1 and EMP3 are two independent tumor predictors that are of great significance for the prognostic prediction of other tumors, and their expression levels may be related to the prognosis of glioma patients." (PMID 37887529, 2023). "However, we looked into the role of EMP3 in glioma cells and confirmed our conclusion." (PMID 37091145, 2023). "Similar to previous studies, S100A4, PLAUR, and EMP3 were found to be associated with glioma progression to high grade and were identified as the hub genes that may affect TAF infiltration in glioma." (PMID 35574375, 2022). "In addition, TAGLN2 and EMP3 were performed in commercially glioma tissue-microarrays." (PMID 33123464, 2020). "In conclusion, EMP3 and CHI3L1 can be used as prognostic indicators in low-grade gliomas, and the OS and DFS of patients with low EMP3 and CHI3L1 are significantly better than those of patients with high EMP3 and CHI3L1." (PMID 37887529, 2023). "Based on the TCGA database, we analyzed the influence of gene changes affecting EMP3 and CHI3L1 expression in glioma patients on the survival time of glioma patients." (PMID 37887529, 2023). "Survival curves for four model genes (ABCC3, EMP3, AL161787.1, and IGFBP2) highlighted IGFBP2 as a significant marker of decreased survival outcomes in glioma patients." (PMID 37928523, 2023).
glioma (continued). "In conclusion, the average expression levels of EMP3 and CHI3L1 were statistically significant among the eight clinical characteristics of glioma patients." (PMID 37887529, 2023). "The results showed that EMP3 positively correlated with CHI3L1 in both primary and recurrent gliomas." (PMID 37887529, 2023). "Another study calculated significant prognostic values for four hub genes (EMP3, PDPN, TAGLN2, and TIMP1) related to m6A regulators, all with high expression in high-grade glioma, and further correlation to IDH status and transcriptome subtype." (PMID 36831575, 2023). "The results indicate that a low expression of EMP3 and CHI3L1 significantly affects patients with low-grade gliomas, showing a better prognosis." (PMID 37887529, 2023). "The current consensus is that EMP3 is a tumor suppressor gene, whereas the current database shows that EMP3 is significantly expressed in GBM and is related to the prognosis of gliomas." (PMID 37091145, 2023). "To further verify the correlation between EMP3 and CHI3L1 in patients with glioma, we analyzed the correlation between these two proteins in patients with primary and recurrent gliomas." (PMID 37887529, 2023). "According to these results, the expression levels of EMP3 and CHI3L1 are significant in the prognostic prediction of both primary and recurrent gliomas." (PMID 37887529, 2023). "Reflections on all-grade glioma patients showed that EMP3 and CHI3L1 showed significant differences in the expression of low-grade and high-grade gliomas." (PMID 37887529, 2023). "In previous studies, EMP3 and CHI3L1 were identified as novel independent predictors of clinical diagnosis, prognosis, and immune infiltration in glioma patients, respectively." (PMID 37887529, 2023). "In our study, we combined EMP3 and CHI3L1, which are correlated in glioma cells and can be combined as prognostic factors for patients with low-grade glioma." (PMID 37887529, 2023). "To investigate the expression levels of EMP3 and CHI3L1 in different tissues, we analyzed the mRNA levels of EMP3 and CHI3L1 in normal brain tissue, low-grade gliomas, and high-grade gliomas." (PMID 37887529, 2023). "We used TCGA and CGGA databases to analyze the effect of EMP3 and CHI3L1 expression on the prognosis of glioma patients and their correlation with gene expression using bioinformation analysis." (PMID 37887529, 2023). "In this study, we analyzed the expression, prognosis, and survival curves of EMP3 and CHI3L1 in low-grade glioma and glioblastoma." (PMID 37887529, 2023). "In our exploration of EMP3 and CHI3L1, we discovered that both proteins are upregulated in malignant tumors such as glioma and are involved in tumor progression through the PI3K/AKT pathway." (PMID 37887529, 2023). "Recently, ABCC3 has been included in gene signatures (ABCC3, CD44, TNFRSF1A, and MGMT24; ABCC3, SMC4, EMP3, WEE1, and HIST1H2BK44) that classify glioma patients in agreement with therapeutic response to chemotherapeutic agents, including TMZ." (PMID 36585418, 2022). "Analysis of TCGA data showed that EMP3 expression is higher in IDH-wt GBM compared to normal brain tissue and IDH-mutant gliomas with the glioma CpG island methylator phenotype (G-CIMP)." (PMID 34067658, 2021). "EMP3 expression was significantly higher in GBM than in non‐neoplastic white matter and led to worse OS rates in WHO grade II‐III glioma." (PMID 34268874, 2021). "The prognostic significance of age related genes IGFBP2, EMP3, TIMP1 and SERPINE1 were further demonstrated in Kaplan-Meier survival analysis in glioma patients." (PMID 32328202, 2020). "Previous results suggested that EMP3 28-32 and IGFBP2 33-35 were critical biomarkers in glioma prognosis." (PMID 32328202, 2020). "We found that patients with both high EMP3 and SERPINE1 expressions were particular with lowest overall survival in glioma patients." (PMID 32328202, 2020). "Based on the average expression level of EMP3 and SERPINE1, glioma patients were divided into four groups." (PMID 32328202, 2020).
glioma (continued). "And as illustrated in the box plots, IGFBP2, EMP3, TIMP1 and SERPINE1 were all highly expressed in glioma tumor tissues, compared with the normal brain tissues." (PMID 32328202, 2020). "Spearman correlation demonstrated a high correlation between EMP3 and SERPINE1 in glioma expression TCGA and GSE43378 datasets (." (PMID 32328202, 2020). "At last, we demonstrate the prognostic effects of combination of EMP3 and SERPINE1 genes in glioma patients." (PMID 32328202, 2020). "Another recent study on high-grade glioma showed high expression of EMP3, particularly in CD44-high glioblastoma, which refuted the result of a prior study on glioma." (PMID 32857809, 2020). "We analyzed expression of PPIC, EMP3 and CHI3L1 in expression profiles acquired from the Gene Expression Omnibus (GEO) database, and glioma datasets acquired from The Cancer Genome Atlas (TCGA)." (PMID 27801851, 2016). "Independent validation with glioma patients tissue (n = 70) and normal brain tissue (n = 19) found PPIC, EMP3 and CHI3L1 were up-regulated in glioma tissue." (PMID 27801851, 2016). "The EMP3 gene has been proposed as a candidate tumor suppressor gene (TSG) on 19q13.3 in several human solid tumors, such as gliomas, neuroblastoma, esophageal squamous cell carcinoma (ESCC), breast cancer, and pheochromocytoma." (PMID 24083241, 2013). "This is in contrast with a previous observation by unsupervised clustering analysis of the DNA hypermethylation profiles in 154 primary gliomas; of the three identified methylation patterns, Class 1 contains both the MGMT and EMP3 genes." (PMID 24083241, 2013). "The mechanism and signaling alterations defined here, while irrelevant for IDH-mutant gliomas that tend to have low EMP3 levels, are likely to be broadly applicable to other non-glioma tumor entities, as their RTK signaling outputs have also been shown to be supported by EMP3." (PMID 37936247, 2023). "Moreover, in this study, we conducted statistical analyses on the role of EMP3 and CHI3L1 in glioma from existing public data and verified the results with a simple qRT-PCR validation in human specimens." (PMID 37887529, 2023). "Conversely, EMP 3 is downregulated in neuroblastoma, glioma, non-small cell lung cancer (NSCLC), and esophageal cancer, where it inhibits cell proliferation." (PMID 37629198, 2023). "Previous studies have shown that EMP3 and CHI3L1 are upregulated in glioma tissues." (PMID 37887529, 2023). "We speculate that targeted inhibitors of EMP3 and CHI3L1 genes may be an effective method to improve the prognosis of glioma patients in the future." (PMID 37887529, 2023). "We revealed that only SRSF1, but not IGFBP2 and EMP3, was markedly reduced by miR-6760-5p mimics but increased by miR-6760-5p inhibitors in glioma tumor cells, suggesting that SRSF1 is the direct target of miR-6760-5p." (PMID 37063420, 2023). "Additionally, we are planning to set up a multicenter study to investigate the correlation between EMP3 and CHI3L1 expression levels and survival outcomes in glioma patients." (PMID 37887529, 2023). "Our study confirmed a correlation between EMP3 and CHI3L1 in glioma cells." (PMID 37887529, 2023). "To investigate the function of EMP3 in GBM, we performed knockdown experiments with siRNAs and found that EMP3 knockdown inhibits the migration and invasion of glioma, but did not affect the proliferation of glioma." (PMID 37091145, 2023). "Therefore, we believe that the expression level of EMP3 and CHI3L1 have guiding significance for the prognosis and survival of patients with low-grade glioma." (PMID 37887529, 2023). "Previous studies have separately investigated the roles of EMP3 and CHI3L1 in gliomas." (PMID 37887529, 2023). "The results showed that EMP3 and CHI3L1 had a specific correlation with the prediction of glioma and could be used as a combined index to judge the prognosis of glioma patients." (PMID 37887529, 2023).
glioma (continued). "The results showed that EMP3 and ITGA5 were most commonly genomically altered and may be involved in glioma progression." (PMID 35647198, 2022). "High GNAI, EMP3, TIMP1, ITGA5, and NMI while low PCDH7, CALCRL, and NFKBIA expressions could lead to poor prognoses in glioma patients." (PMID 35647198, 2022). "Experimental findings based on glioma and non-glioma models have demonstrated the role of EMP3 in the regulation of several membrane proteins known to drive IDH-wt GBM." (PMID 34067658, 2021). "Glioma patients with low CDHR1 and high EMP3 expression had worse clinical outcomes." (PMID 34335936, 2021). "The prognostic effects of EMP3 28-32 and IGFBP2 33-35 in glioma patients are extensively studied." (PMID 32328202, 2020). "Furthermore, we demonstrated that EMP3 and SERPINE1 were connected with each other and the combination of EMP3 and SERPINE1 had better prognostic effects in glioma patients." (PMID 32328202, 2020). "However, the inner mechanisms of how EMP3 and IGFBP2 involving the glioma overall survival are unclear." (PMID 32328202, 2020). "Interestingly, EMP3 and SERPINE1 are connected with each other and the combination of EMP3 and SERPINE1 genes have better prognostic effects in glioma patients." (PMID 32328202, 2020). "As most previous studies regarding EMPs had used epithelial carcinoma and a few had used glioma, this study was important as it determined the role of EMP3 in non-epithelial tumors, similar to the present study." (PMID 32857809, 2020). "Differential EMP3 mRNA expression was observed in gliomas, with the highest expression seen in GBMs (GBMs Vs non-tumor, P < 0.0001; GBM Vs grade II or grade III astrocytomas/oligodendrogliomas, P < 0.05; Grade II astrocytomas Vs non-tumor, P < 0.05." (PMID 27527869, 2017). "The animals were intracranially inoculated with LN18 glioma cells with or without EMP3 knockdown (n = 16)." (PMID 27527869, 2017). "Taken together, the results suggest that expressions of PPIC, EMP3 and CHI3L1 may play a vital role in glioma progression." (PMID 27801851, 2016). "We determined that PPIC, EMP3 and CHI3L1 were up-regulated in the glioma tissue." (PMID 27801851, 2016). "Intersection of the DEPGs revealed a total of three common DEPGs—PPIC, EMP3 and CHI3L1—suggesting that these common DEPGs may be potential prognostic indicators of glioma progression." (PMID 27801851, 2016). "After intersecting DEPGs generated from the two datasets, three common DEPGs (PPIC, EMP3 and CHI3L1) were identified, suggesting that these genes may be potential predictors of prognosis in high-grade gliomas patients." (PMID 27801851, 2016). "EMP3 expression is significantly higher in glioma cells than in non-neoplastic white matter." (PMID 37887529, 2023). "Therefore, EMP3 and CHI3L1 may affect the proliferation, apoptosis, and death of glioma cells by regulating CD44 and affecting TGF-β, ERK, Akt, and other pathways." (PMID 37887529, 2023). "Therefore, we propose that PPIC, EMP3 and CHI3L1 may be suitable as prognostic genes or therapeutic targets for high grade gliomas." (PMID 27801851, 2016). "The expression levels of EMP3 and CHI3L1 in wild-type IDH-1, non-1P19Q co-deletion, and MGMT non-methylated gliomas were higher than in others." (PMID 37887529, 2023). "High levels of CHI3L1 and EMP3 as well as FAPB7 and POSTN were reported as negative prognostic biomarkers in glioma." (PMID 29523123, 2018). "In addition, in this paper, we only studied the relationship between the expression levels of EMP3 and CHI3L1 and the prognosis of glioma patients, without studying the specific pathway, which is also the focus of our research in the next stage." (PMID 37887529, 2023). "Additionally, our results showed that EMP3 and CHI3L1 expression was significantly higher in gliomas compared to non-tumor brain tissue." (PMID 27801851, 2016).
glioblastoma (21 papers, 2016 to 2025). The most malignant astrocytic tumor (WHO grade IV). "It has been reported that EMP3 has a multifunctional role in the regulation of membrane receptors associated with IDH wild-type glioblastoma, and that it potentially “mediates glioblastoma-associated macrophage infiltration to drive T cell exclusion”." (PMID 39941811, 2025). "In this study, we conducted an in-depth exploration of the clinicopathological characteristics, prognostic implications, and diagnostic potential of EMP3 in glioblastoma patients, employing both bulk and single-cell analysis methods." (PMID 38229014, 2024). "Epithelial membrane protein 3 (EMP3) is an N-glycosylated tetraspanin implicated in isocitrate dehydrogenase-wild-type (IDH-wt) glioblastoma (GBM)." (PMID 37936247, 2023). "EMP3 plays an important role in the regulation of membrane receptors associated with IDH-Wild type glioblastoma." (PMID 36727078, 2022). "EMP3 regulates membrane receptors associated with IDH-wild type glioblastoma." (PMID 38171932, 2023). "Both PDPN and EMP3 were found to be correlated with clinical outcomes in spheroid cultures derived from 20 glioblastomas." (PMID 39941811, 2025). "In previous research on glioblastoma, Qun Chen and colleagues found that EMP3 promotes the migration and M2 polarization of monocyte-derived macrophages and downregulates the production of chemokines induced by interferon, CXCL9 and CXCL10, by macrophages." (PMID 41000385, 2025). "Comparing 1464 EMT-associated genes in glioblastoma with the pan-cancer dataset, we uncovered three key genes: VIM, EMP3, and AHNAK." (PMID 38229014, 2024). "Transwell migration assay and wound healing assay were used to assess the effect of EMP3 on glioblastoma migration." (PMID 38229014, 2024). "In our study, silencing of EMP3 inhibits the malignant behavior of glioblastoma cells by regulating the EMT process mechanistically." (PMID 38229014, 2024). "Consistently with these previous findings, our single-cell analysis revealed EMP3 correlates with EMT score in high-grade glioblastoma cells." (PMID 38229014, 2024). "To determine the biological function of EMP3 in glioblastoma, we knocked down EMP3 in two glioblastoma cell lines (U87 MG and U251 MG) by transient transfection with siRNA (si-EMP3-1,si-EMP3-2 and si-EMP3-3) for 72 h cultured with siRNA." (PMID 38229014, 2024). "EMP3 is regarded as an immunosuppressive factor in glioblastoma because it mediates M2 TAM infiltration and suppresses T-cell infiltration to facilitate tumor progression." (PMID 37543576, 2023). "Overall, our results reveal that EMP3 can predict poor prognosis in glioblastoma patients." (PMID 38229014, 2024). "The effect of EMP3 on glioblastoma proliferation was examined using the CCK-8 assay." (PMID 38229014, 2024). "EMP3 is a EMT associated gene in multiple types of malignant cancer and in high-grade glioblastoma." (PMID 38229014, 2024). "To determine the role of EMP3 on EMT in glioblastoma, we first performed a correlation analysis of gene expression, which showed that EMP3 was positively correlated with VIM, FOS, SNAI2 and TWIST1 (p < 0.001, R: VIM: 0.754, FOS:0.382, SNAI2: 0.498, TWIST1: 0.605)." (PMID 38229014, 2024). "Furthermore, EGFR-dependent patient-derived glioblastoma stem cells display a transcriptomic signature consistent with reduced CDK2 activity, as well as increased susceptibility to CDK2 inhibition upon EMP3 knockdown." (PMID 37936247, 2023). "We observed that the expression of EMP3 was elevated in glioblastoma." (PMID 34268874, 2021). "The effect of EMP3 depletion was examined in mice with LN18 glioblastoma subcutaneous xenografts." (PMID 27527869, 2017). "Interestingly, EMP3 demonstrated a unique connection with mesenchymal transition specifically in aggressive glioblastoma, while not showing a similar association in low-grade oligodendroglioma or IDH-mutant astrocytoma." (PMID 38229014, 2024).